SNORA57 (small nucleolar RNA, H/ACA box 57)
Synonyms: U99
Gene: Small nucleolar RNA gene on chromosome 11 (62,665,422 to 62,665,570, forward strand). Ensembl gene ENSG00000206597.
Gene Ontology:
Biological process: RNA processing
Cellular component: nucleolus
Homologues: Orthologues: chimpanzee SNORA57 (99% identical), mouse Snora57 (89% identical), pig SNORA57 (89% identical), dog SNORA57 (88% identical), rat LOC120100346 (87% identical), rabbit SNORA57 (86% identical), guinea pig SNORA57 (81% identical).